LGR5 (leucine rich repeat containing G protein-coupled receptor 5)
Description:
Receptor for R-spondins that potentiates the canonical Wnt signaling pathway and acts as a stem cell marker of the intestinal epithelium and the hair follicle. Upon binding to R-spondins (RSPO1, RSPO2, RSPO3 or RSPO4), associates with phosphorylated LRP6 and frizzled receptors that are activated by extracellular Wnt receptors, triggering the canonical Wnt signaling pathway to increase expression of target genes. In contrast to classical G protein-coupled receptors, does not activate heterotrimeric G proteins to transduce the signal. Involved in the development and/or maintenance of the adult intestinal stem cells during postembryonic development.
Synonyms: GPR49; GPR67; HG38; FEX; GRP49
Tractability: Small molecule: it belongs to a druggable protein family. Antibody: its Gene Ontology location is reachable by antibodies, with high confidence; UniProt places it where antibodies can reach, with medium confidence; UniProt predicts a signal peptide or a membrane-spanning region.
Gene: Protein-coding gene on chromosome 12 (71,439,797 to 71,586,310, forward strand). Ensembl gene ENSG00000139292.
Subcellular location: Cell membrane; Golgi apparatus, trans-Golgi network membrane
Subcellular location (Human Protein Atlas): Nucleoplasm; Primary cilium transition zone; Vesicles; Basal body; Centrosome
Pathways (Reactome):
Signal Transduction: Regulation of FZD by ubiquitination
Gene Ontology:
Molecular function: G protein-coupled receptor activity; protein binding; transmembrane signaling receptor activity; protein-hormone receptor activity
Biological process: positive regulation of canonical Wnt signaling pathway; G protein-coupled receptor signaling pathway; positive regulation of Wnt signaling pathway
Cellular component: plasma membrane; trans-Golgi network membrane; Golgi apparatus; membrane
Genetic constraint (gnomAD): Loss-of-function variants: 23 observed, 44.12 expected, observed/expected ratio (o/e) 0.52, 90% interval 0.37 to 0.74. The upper end of that interval is the gene's LOEUF score, 0.74, which puts it in group 3 of 6, group 1 being the genes least tolerant of losing a copy. Missense variants: 835 observed, 886.43 expected, observed/expected ratio (o/e) 0.94, 90% interval 0.89 to 1. Synonymous variants: 338 observed, 356.53 expected, observed/expected ratio (o/e) 0.95, 90% interval 0.87 to 1.04.
Homologues: Orthologues: chimpanzee LGR5 (99% identical), macaque LGR5 (98% identical), rabbit LGR5 (91% identical), pig LGR5 (90% identical), guinea pig LGR5 (87% identical), rat Lgr5 (86% identical), mouse Lgr5 (86% identical), tropical clawed frog lgr5 (74% identical), dog LGR5 (71% identical), Caenorhabditis elegans sma-10 (18% identical), Drosophila melanogaster kek3 (15% identical), Drosophila melanogaster Con (13% identical), and 1 more. Paralogues in human: LGR6 (54% identical), LGR4 (47% identical), LRIG1 (21% identical), LRIG2 (21% identical), LRIG3 (20% identical), TRIL (15% identical), CPN2 (13% identical), LRIT3 (13% identical), CHADL (13% identical), LRRTM2 (12% identical), LGI1 (12% identical), LRIT1 (12% identical), and 10 more.
Diseases named in the same sentence as LGR5 in open-access papers:
LGR5 is named in the same sentence as 233 diseases in open-access papers, as found by Europe PMC text mining. Sharing a sentence is not in itself a finding about the gene and the disease. The quoted sentences say what the papers report.
colorectal cancer (224 papers, 2011 to 2026). A primary or metastatic malignant neoplasm that affects the colon or rectum. "The upregulation of LGR5 has been associated with unfavorable prognosis and resistance to chemotherapy among patients with colorectal cancer." (PMID 39417449, 2024). "For instance, αSMA+ cancer‐associated fibroblasts in colorectal cancer (CRC) have been shown to exert tumor‐restraining functions by suppressing LGR5+ TICs and promoting anti‐tumor immunity." (PMID 37578396, 2023). "LGR5 silenced colorectal cancer cells tended to be more mesenchymal, while overexpression of LGR5 was linked to a more epithelial phenotype." (PMID 37770230, 2023). "Particularly, the decreased expression of Lgr5, one of the most important genes for stem cell hierarchy and maintenance in colorectal cancer, underlines the stem cell activity of salinomycin." (PMID 30763370, 2019). "In that study the scientists observed a higher activation of the Wnt signalling together with a higher proliferative ability upon overexpression of both LGR5 splice variants compared with the cells which overexpressed only LGR5FL in colorectal cancer cells." (PMID 30770730, 2019). "Apart from its crucial role in the maintenance of stemness, the expression profile of LGR5 is directly associated with carcinogenesis and progression in papillary thyroid cancer, colorectal cancer, and breast cancer." (PMID 30089773, 2018). "It was previously reported that loss of lgr5 expression is seen in approximately 40% colorectal cancer." (PMID 26599100, 2015). "Colorectal cancer patients with high expression of an intestinal stem cell gene signature, including LGR5 and EPHB2, have a 10-times higher risk of relapse compared to patients with low levels." (PMID 26367378, 2015). "Over-expression of LGR5 has been linked to clinically aggressive disease in colorectal carcinoma as well as several other epithelial malignancies." (PMID 23596566, 2013). "In human cancer, overexpression of LGR5 has been noted in up to 90% of hepatocellular carcinomas with β-catenin mutations and in a large proportion of colorectal carcinomas, where APC mutations and hence dysregulated wnt signalling are preponderant." (PMID 21829496, 2011). "OLFM4, a glycoprotein belonging to the olfactomedin family, is expressed in stem cells located at the base of intestinal crypts and is associated with colorectal cancers through its colocalization with the G-protein-coupled receptor 5 (Lgr5) on columnar stem cells in the crypt base." (PMID 39861713, 2025). "It has been reported that decreased LGR5 expression may be associated with abnormal methylation in colorectal cancer and bile duct cancer." (PMID 35123536, 2022). "In stage IV colorectal cancer, high Lgr5 expression is associated with poor prognosis." (PMID 30279970, 2018). "Leucine-rich repeat-containing G-protein coupled receptor 5/G-protein coupled receptor 49 (Lgr5/GPR49) was originally identified as a Wingless-related integration site (Wnt) target gene encoding an orphan G-protein-coupled receptor in colorectal cancer cell-lines." (PMID 29056739, 2016). "In addition, overexpression of LGR5 is associated with a poor prognosis in colorectal cancer patients." (PMID 25950950, 2015). "In addition, we also found that lgr5 methylation was significantly associated with better prognosis among colorectal cancer patients." (PMID 26599100, 2015). "Furthermore, Wnt signaling pathway plays an important role in the maintenance of CSCs, but elevated expression of several Wnt target genes, including ASCL2 and LGR5, is actually associated with good prognosis in colorectal cancer." (PMID 25237769, 2014). "They conclude that LGR5 may be important in restricting stem cells to their niche and loss of LGR5 may contribute to the invasive phenotype of colorectal carcinoma." (PMID 22530031, 2012).
colorectal cancer (continued). "Moreover, the expression of LGR5/GPR49 mRNA was significantly associated with poor prognosis for disease-free survival of colorectal cancer patients." (PMID 21978106, 2011). "We examined the relationship between mismatch repair (MMR) protein deficiency and LGR5 expression in poorly differentiated (PD) colorectal carcinoma (CRC)." (PMID 32293346, 2020). "Furthermore, lgr5 methylation significantly associated with higher tumor grade, and negative distant metastasis (p < 0.05), as well as better prognosis (p = 0.001) in patients with colorectal cancer." (PMID 26599100, 2015). "Colorectal cancer is initiated by loss of APC, which drives expansion of LGR5+ intestinal stem cell (ISC) populations." (PMID 41856980, 2026). "Studies have revealed that specific genes and markers, such as the Wnt target gene and LGR5, significantly impact colorectal cancer (CRC) tumor plasticity." (PMID 41013839, 2025). "Researchers have observed that more differentiated cancer cells can redifferentiate into Lgr5+ cells, thereby replenishing the stem cell pool in colorectal cancer." (PMID 40665579, 2025). "In an established orthotopic mouse model of colorectal cancer, organoids with an enhanced stemness phenotype (Lgr5+) disseminated to liver as early as 3 weeks after injection." (PMID 41346572, 2025). "In colorectal cancer, LGR5 is often highly expressed in tumor-initiating cells and is associated with enhanced tumorigenicity, chemoresistance, and poor prognosis." (PMID 41194856, 2025). "Research indicates that many markers and genes, including the Wnt target gene and LGR5, are essential for this plasticity in colorectal cancer." (PMID 41013839, 2025). "As previously discussed, LGR5+ colorectal cancer stem cells upregulate the transcription factor SOX17, which suppresses expression of the stemness marker LGR5." (PMID 41346579, 2025). "LGR5, a stem cell marker, is overexpressed in several types of cancer, including glioblastoma, cervical, breast, and colorectal cancer." (PMID 40210723, 2025). "For example, the quiescent state (G0 phase) of CSCs renders them insensitive to chemotherapeutic agents that act on proliferating cells, such as the quiescent LGR5+p27+ CSCs in colorectal cancer, which are resistant to chemotherapy and drive recurrence." (PMID 40665579, 2025). "In conclusion, CDH17 plays a crucial role in maintaining colorectal cancer cell stemness and chemoresistance via LGR5/Wnt/MYC signaling and SLC38A5 expression." (PMID 40595509, 2025). "This represents the first report of differential FXR expression in HCC CSCs, despite previous studies indicating that the selective activation of intestinal FXR can inhibit the abnormal proliferation of Lgr5+ cells and impede colorectal cancer progression." (PMID 39940889, 2025). "Our analysis identified stem cells, cancer stem cells, intestinal stem cells, Wnt pathway, colorectal cancer, and organoids as the most frequent terms highlighting their centrality in LGR5 research." (PMID 41194856, 2025). "CD44 and Lgr5 were surface markers of colorectal cancer stem cells, which played important roles in colorectal cancer metastasis and progression." (PMID 40611658, 2025). "Further investigation found that the TDO2-AHR pathway directly regulates the expression of Wnt signal target gene LGR5 to maintain colorectal cancer stemness and regulate the development of colorectal cancer." (PMID 40136551, 2025). "Research in colorectal cancer models reveals that chemotherapy‐resistant, dormant Lgr5+p27+ CSCs reignite tumor growth through the COL17A1–FAK–YAP pathway." (PMID 41346572, 2025). "CNA3103 incorporates a CD28 costimulatory domain and a PD-1 blocking domain to enhance its function and persistence against LGR5-positive colorectal cancer cells." (PMID 39417449, 2024).
colorectal cancer (continued). "One potential antigen target for colorectal cancer is leucine-rich repeat-containing G-protein-coupled receptor 5 (LGR5), a stem cell marker that exhibits high expression levels in colorectal cancer and other malignancies." (PMID 39417449, 2024). "LGR5 expression in LN and clinicopathological characteristics of patients with colorectal cancer and lymph node metastasis." (PMID 38787285, 2024). "Recent studies have identified that Lgr5 positive cells are required for metastasis in the murine models of colorectal cancer." (PMID 38659853, 2024). "LGR5 expression in LN and clinicopathological characteristics in patients with colorectal cancer and LN metastasis." (PMID 38787285, 2024). "In a recent study, potential strategies for targeting Lgr5+ colorectal cancer cells are discussed, including the use of CAR-T cell therapy." (PMID 39417449, 2024). "Since Lgr5+ stem cells play important roles in colorectal cancer (CRC) development, we examined the role of Bcl11b in this process." (PMID 39433900, 2024). "Lgr5 identifies CSCs in genetically engineered mouse models that mimic the progression of human colorectal cancer." (PMID 39225547, 2024). "An analogous observation was reported in colorectal cancer, where selective ablation of LGR5+ CSCs in organoids leads to initial tumor regression, followed by regrowth driven by LGR5+ CSCs reemerging from the LGR5– population." (PMID 38236642, 2024). "In the present study we establish that expression levels of LGR5 mark distinct mechanical phenotypes in patient-derived colorectal cancer organoids." (PMID 38637494, 2024). "For instance, targeting Lgr5 in colorectal cancer, DLL3 in pulmonary neuroendocrine tumors, and CXCR1 in breast cancer has been reported to reduce the CSC population." (PMID 39420119, 2024). "Knowing that colorectal cancer tumors contain LGR5-positive CSCs, we analyzed the presence of LGR5+ cells in two colorectal cancer tumors by immunofluorescence (together with CD90 and EpCAM) or by flow cytometry (together with AF)." (PMID 39225547, 2024). "Leucine‐rich repeat‐containing G protein‐coupled receptor 5 (LGR5), a significant cancer stem cell marker in colorectal cancer (CRC), lacks lymph node (LN) expression studies." (PMID 38787285, 2024). "Leucine-rich repeat-containing G-protein receptor 5 (LGR5) was originally identified as a target gene of oncogenic Wnt signalling in colorectal cancer cells." (PMID 39169164, 2024). "The hierarchical model also applies to colorectal cancer, where Lgr5 (Leucine-rich repeat-containing G protein-coupled receptor 5) receptor is a marker of stem cells in the normal intestinal epithelium." (PMID 37259089, 2023). "Prognostic indicator based on TCGA colorectal cancer patients containing four key radiation resistance genes (LGR5, KCNN4, TNS4, CENPH) was established." (PMID 37328854, 2023). "CD133 and Lgr5 cells are independent prognostic markers for low survival and drug resistance in colon human colorectal cancer patients." (PMID 36831488, 2023). "In further studies, CBB1003 displayed weak cell growth inhibition (IC50 = 250 μM) in colorectal cancer (CRC) through downregulation of leucine-rich repeat-containing G-protein-coupled receptor 5 (LGR5), a CRC stem cell marker involved in carcinogenesis." (PMID 36817147, 2023). "Further analyses showed that αSMA+ CAFs in colorectal cancer inhibited the proliferation of Lgr5+ CSCs and promoted the differentiation of CSCs through BMP4/TGFβ1 signaling pathway, exerting tumor suppressive effects and inhibiting the CRC progression." (PMID 37124519, 2023).
colorectal cancer (continued). "It has previously been demonstrated by at least two independent meta-analyses that in contrast to the prognostic effect of WNT5A expression, patients with elevated expression of the LGR5 protein in their colorectal cancer tissue had poor overall survival." (PMID 37998393, 2023). "Yet, expression of the Wnt target gene LGR5 must be precisely tuned to facilitate plasticity at distinct stages of colorectal cancer pathogenesis." (PMID 36833408, 2023). "Elevated expression of CSC markers CD166, ALDH1A3, CD133, and LGR5 was consistent with their role in drug resistance of colorectal carcinoma and correlation with a poor prognosis for patients." (PMID 37791907, 2023). "A recent study revealed that leucine‐rich repeat containing G protein‐coupled receptor 5 (LGR5) was over‐expressed in colorectal cancers." (PMID 34793617, 2022). "In recent years, many studies have shown that LGR5 is highly expressed in multiple malignant tumor types, including colorectal cancer, ovarian cancer, hepatocellular carcinoma, basal cell carcinoma, and esophageal adenocarcinoma." (PMID 36288272, 2022). "On the basis of recent reports that apc mutation occurring in lgr5+ stem cells is the origin of colorectal cancer (CRC), organoid model systems, using apc-mutated lgr5+ stem cells, have been used as a powerful CRC model system." (PMID 36354674, 2022). "Leucine-rich repeat-containing G-protein-coupled receptor 5 (LGR5) is a strong cancer stem cell marker in colorectal cancer; however, there are many unclear aspects of LGR5 expression in pancreatic cancer." (PMID 35123536, 2022). "Other studies have shown that LGR5 plays an inhibitory role in colorectal cancer (CRC) progression in colorectal cancer." (PMID 36288272, 2022). "Recent data establish a logarithmic expansion of leucine rich repeat containing G protein coupled receptor 5–positive (Lgr5+) colonic epithelial stem cells (CESCs) in human colorectal cancer (CRC)." (PMID 35260534, 2022). "A mouse model of colorectal cancer showed that selective Lgr5+ CSC ablation inhibits primary tumor growth and distinct CSC dependencies for primary vs. metastatic tumor growth." (PMID 35773697, 2022). "In colorectal cancer, a relationship was highlighted between poor differentiation, lymph node metastasis, and low LGR5 expression due to hypermethylation." (PMID 35123536, 2022). "In mouse models, genetic inactivation of the key colorectal cancer (CRC) driver gene Adenomatous Polyposis Coli (Apc) in Lgr5+ve cells precipitated rapid tumor induction, confirming CBCs as a cell-of-origin in intestinal tumorigenesis." (PMID 35931031, 2022). "It has been reported that LGR5 is strongly expressed in differentiated adenocarcinomas, as well as in other carcinomas such as colorectal cancer." (PMID 35123536, 2022). "In colorectal cancers, LGR5 + cells have been demonstrated to act as cancer stem cells fueling tumor growth and metastasis." (PMID 34493772, 2021). "Three-dimensional colorectal cancer organoid models, expressing LGR5, showed increased resistance to 5-fluorouracil and irinotecan in comparison with non-stem-cell lines of colorectal cancer." (PMID 34884696, 2021). "Homeostatic LGR5 + stem cells contribute to various cancers such as colorectal cancers, gastric cancers, and squamous cell skin carcinomas when oncogenic mutations occur." (PMID 34493772, 2021). "Immunofluorescent staining with HCT116/FU and HCT116 sphere cells indicated that AB4 treatment decreased the expression levels of LGR5, which was an important biomarker for colorectal cancer stem cells." (PMID 34890366, 2021). "Colorectal cancer models have demonstrated the need for Lgr5+ CSCs to initiate and maintain full-blown metastasis." (PMID 33671641, 2021).